TLR4 (toll like receptor 4)
Diseases named in the same sentence as TLR4 in open-access papers (continued):
Sharing a sentence is not in itself a finding about the gene and the disease.
breast cancer (continued). "Similar results were shown in human breast cancer cell line, where downregulation of TLR4 significantly reduced tumor cell proliferation." (PMID 22110526, 2011). "The results suggested that LPS upregulated the MTDH expression in time-dependent and concentration-dependent manners in TLR4 positive breast cancer cells." (PMID 22195048, 2011). "LPS, the ligand of TLR4, was reported to increase the lung metastasis in 4T1 mouse mammary carcinoma cells." (PMID 22195048, 2011). "TLR4AsiRNA directed targeting of TLR4 is a promising candidate for molecular therapy of breast cancer." (PMID 20618976, 2010). "Recombinant plasmids named TLR4AsiRNA, TLR4BsiRNA and TLR4CsiRNA specific to TLR4 were transfected into human breast cancer cell line MDA-MB-231 with LipfectamineTM2000 reagent." (PMID 20618976, 2010). "Knockdown of TLR4 gene in MDA-MB-231 resulted in a dramatic reduction of breast cancer cell viability." (PMID 20618976, 2010). "This not only strengthens neutrophil self‐recruitment via the CXCL2 autocrine but also promotes neutrophil secretion of IL‐1β through the TLR4‐NFκβ pathway, thereby remodeling the lung microenvironment and contributing to the promotion of lung metastasis of breast cancer." (PMID 39630109, 2025). "Notably, F. nucleatum is known to activate NF-κB signaling via TLR4, thereby promoting chronic inflammation and immune evasion, mechanisms well-documented in colorectal and breast cancers." (PMID 40941635, 2025). "In basal-like breast cancer, we found that a low WWOX/HIF1A ratio is associated with particularly aggressive disease because it promotes EMT via ZEB1 and ADAM9, facilitates ECM remodelling via MMP2 and ITGA1, and enables immune evasion via NOTCH1 and TLR4." (PMID 41007296, 2025). "In addition, the level of SP1 in TDEs increases, which favors the secretion of IL‐1β by neutrophils through the activation of the TLR4‐NFκβ pathway, ultimately aggravating lung metastasis of breast cancer." (PMID 39630109, 2025). "In addition, the authors evidenced that PAMPs, such as LPS, activate the TLR4 pathway in breast cancer cell lines." (PMID 40647480, 2025). "This review aims to systematically analyze TLR-4-mediated chemoresistance mechanisms in ovarian cancer, breast cancer, liver cancer, cervical cancer, colorectal cancer and other malignancies induced by drugs like paclitaxel, cisplatin, docetaxel (DTX), 5-fluorouracil." (PMID 40404908, 2025). "Similarly, in luminal breast cancer, autophagic CAFs release HMGB1that activates TLR4 on cancer cells to maintain their stemness and tumorigenicity, linking stromal autophagy to the preservation of a treatment-resistant cancer cell population." (PMID 41465435, 2025). "Toll-like receptor type 4 (TLR4) and Advanced Glycation End Products Receptor (AGER/RAGE) have been implicated in breast cancer, and have been shown to promote tumor growth, metastasis, and resistance to therapy by modulating the tumor microenvironment and inflammatory pathways." (PMID 40647480, 2025). "Breast cancer biopsies present higher expression levels of TLR4 compared to normal breast tissues." (PMID 40647480, 2025). "Skimmianine-mediated TNF-α suppression may contribute to decreased inflammation and immune evasion, aligning with studies showing that TLR4 targeting decreases proliferation and cytokine secretion in breast cancer cells." (PMID 40430573, 2025). "This approach may involve combining TLR4 targeting with existing breast cancer treatments that modulate the tumor microenvironment and enhance anti-tumor immunity." (PMID 38903515, 2024). "Toll-like receptors (TLRs) constitute a broad family of pattern recognition receptors crucial for initiating inflammatory reactions, among which TLR4 is a prominent member often found to be overexpressed in several human cancers, including prostate cancer and breast cancer." (PMID 39390599, 2024). "Furthermore, TLR4 agonists have demonstrated anti-metastatic effects in specific breast cancer models." (PMID 38903515, 2024).
breast cancer (continued). "Targeting TLR4 signaling pathways, either directly or indirectly, may offer novel therapeutic strategies for breast cancer treatment." (PMID 38903515, 2024). "Therefore, meta-analysis is the most effective method to deeply understand the impact of TLR4 on clinicopathologic features and prognosis of breast cancer patients." (PMID 38463226, 2024). "TLR4 activation, whether by lipopolysaccharides (LPS) or endogenous ligands, has been found to significantly promote various cancerous behaviors in breast cancer cells in vitro." (PMID 38903515, 2024). "Notably, the expression levels of TLR4 and its downstream adaptor protein MyD88 are significantly elevated in breast cancer compared to adjacent normal tissue, and the upregulation is associated with a poor prognosis." (PMID 38725852, 2024). "Moreover, TLR4 activation directly influences the behavior of breast cancer cells, promoting their proliferation, survival, and resistance to apoptosis, which collectively contribute to tumor progression." (PMID 38903515, 2024). "Atractylenolide-I, a major bioactive component from Atractylodes macrocephala, suppressed tumorigenesis of breast cancer by inhibiting TLR4-mediated NF-κB signaling pathway and sensitized TNBC cells to paclitaxel by blocking connective tissue growth factor expression." (PMID 38466979, 2024). "Several studies indicate that TLR4 activation may impede breast cancer cell growth and prompt apoptosis." (PMID 38903515, 2024). "Additionally, recent findings indicate that small extracellular vesicles derived from Fusobacterium nucleatum facilitate tumor growth and metastasis via TLR4 in breast cancer." (PMID 38903515, 2024). "Interestingly, TLR4 signaling appears to intersect with estrogen receptor signaling pathways in breast cancer." (PMID 38903515, 2024). "The prognostic value of Toll-like receptor 4 (TLR4) in breast cancer remains to be determined." (PMID 38463226, 2024). "However, our results show that BCA2 promotes breast cancer progression and acts by promoting TLR4-mediated NF-κB activation." (PMID 38725852, 2024). "Although two studies had the same first author and the sample selection time overlapped, the samples were from different databases, so we included these studies and evaluated the relationship between TLR4 expression and survival outcomes in breast cancer patients." (PMID 38463226, 2024). "Furthermore, MyD88’s protein expression level exhibits a positive correlation with axillary lymph node metastasis and histological grade, while the co-expression of TLR4 and MyD88 is positively correlated with breast cancer cell metastasis." (PMID 38347830, 2024). "From our main analysis results, high TLR4 expression is associated with lymph node metastasis, larger tumor size (≥2 cm), later clinical stage, negative PR expression and shorter DFS, suggesting poor prognosis in breast cancer patients." (PMID 38463226, 2024). "Additionally, TLR4 activation in breast cancer cells modulates immune responses, promoting immune evasion through the secretion of immunosuppressive factors and inhibition of anti-tumor immune responses." (PMID 38903515, 2024). "TLR4 functions as a receptor for resistin, an adipokine related to obesity and T2DM which has been implicated in tumorigenesis through PI3K-AKT and MAPK pathways and is suspected to confer resistance to chemotherapy in breast cancer cells." (PMID 37626871, 2023). "Additionally, glycation has been linked to activating the RAGE/TLR4/MyD88 signaling pathway and upregulating MMP9 expression in breast cancer, thus increasing migration and invasion." (PMID 37174618, 2023). "Additionally, the expression level of MyD88 alongside TLR4 was also found to be positively correlated with axillary lymph node metastasis and histological-grade breast cancer development." (PMID 37822929, 2023).
breast cancer (continued). "Thus, and to the best of our knowledge, our study is the first to report that targeting SOCE can influence the TLR4-induced migration and proliferation of breast cancer cells, as well as the production of inflammatory and cancer-related genes in these cells." (PMID 37371732, 2023). "Thus, the current study intended to delineate the role of SOCE in the TLR4-induced inflammation, migration, and proliferation of breast cancer cells." (PMID 37371732, 2023). "Besides, it can inhibit tumorigenesis of breast cancer through suppressing the nuclear factor-κB (NF-κB) pathway mediated by Toll-Like Receptor 4 (TLR4)." (PMID 37700383, 2023). "Additionally, the siRNA-mediated knockdown of TLR4 suppresses the proliferation and release of the inflammatory cytokines, IL-6 and IL-8, in breast cancer cells." (PMID 37371732, 2023). "TLR4 antagonist ATL I inhibits the TLR4/NF-κB signaling pathway in breast cancer cells and reduces NF-κB-regulated cytokines, cell proliferation, migration, invasion, and promotes apoptosis, leading to an anti-breast cancer effect." (PMID 37241729, 2023). "In addition, TLR4 activation has been shown to promote invasiveness of human breast cancer cells and to be overexpressed in patients with lymph node metastasis." (PMID 37112730, 2023). "TLR4 activation promotes the migration and proliferation of breast cancer cells." (PMID 37371732, 2023). "Our study herein was designed to evaluate whether the SOCE pathway can influence the TLR4 signaling in breast cancer cells and ultimately affect inflammation-induced cancer progression processes." (PMID 37371732, 2023). "TLR4, as a receptor of resistin, which has high expression in human breast cancer, also mediates the promoting effect of resistin on epithelial-to-mesenchymal transition and stemness in breast cancer, combined with the downstream NF-κB/STAT3 pathway." (PMID 37576399, 2023). "Another study revealed that atractylenolide-I could inhibit breast cancer genesis via inhibiting the TLR4-mediated NF-κB signaling pathway." (PMID 35251139, 2022). "Furthermore, resistin was proved to accelerate EMT and breast cancer cell stemness by toll-like receptor 4 (TLR4)-induced NF-κB activation." (PMID 35701840, 2022). "Furthermore, MIFs release impacts host immune responses in the TME by regulating the HMGB1/TLR4/NF-κB axis 61, and all these interactions contribute to breast cancer metastasis." (PMID 35637945, 2022). "However, the microbiota‐derived LPS‐mediated regulation of S100A7 and TLR4 in breast cancer is yet unexplored." (PMID 33969603, 2022). "Together, our findings previously and in this report suggest that TNFα is essential for an IAP antagonist to treat cancer by inducing cancer cell apoptosis rapidly, and bacterial component LPS can also induce breast cancer cell apoptosis through TLR4 stimulating TNFα production by the host cells." (PMID 36119107, 2022). "NKILA is another lncRNA upregulated by TLR-4 stimulation in MDA-MB-231 in breast cancer cells." (PMID 35895506, 2022). "According to the previous reports, PTX could activate toll-like receptor-4 (TLR4) to enhance systemic inflammation and promote lymphangiogenesis and breast cancer lymphatic metastasis." (PMID 35280672, 2022). "To further elucidate the specific cell–cell communication by S100A8/S100A9 signaling in the tumor ecosystem, we analyzed RAGE and TLR4 signaling via measuring ligand and receptor expression in different cell types using single-cell RNA-seq data from two breast cancer metastases." (PMID 35440136, 2022). "Interestingly, whole‐body deletion of TLR4 enhances the tumor growth and distant metastasis in TLR4 knockout transgenic breast cancer mouse model." (PMID 33969603, 2022). "Furthermore, we have also shown that expression of S100A7 is inversely correlated with TLR4 expression in breast cancer patients, especially in basal intrinsic subtype of breast cancer." (PMID 33969603, 2022).
breast cancer (continued). "MiR-361-5p could target TLR4, and miR-361-5p mimics could positively regulate the viability of paclitaxel-resistant breast cancer cells treated with paclitaxel." (PMID 36132137, 2022). "In previous studies, we demonstrated that stimulating TLR4 with LPS reduces microglia-assisted breast-cancer-cell invasion and that the myeloid compartment of BM can be re-educated towards a more anti-metastatic phenotype in breast-cancer colonization models." (PMID 36224342, 2022). "There are more reports about HMGB1/TLR4 interactions in breast cancer progression." (PMID 35637945, 2022). "Moreover, our TMA analysis highlighted the inverse correlation of S100A7 with TLR4 expression in breast cancer patients." (PMID 33969603, 2022). "Interestingly, we discovered a decreased expression of TLR4 only in the basal intrinsic subtype of breast cancer compared with normal breast tissues." (PMID 33969603, 2022). "In particular, EECP and CAPE inhibited TLR-4 signaling pathway molecules such as TLR-4, MyD88, IRAK4, TRIF, and NF-κBp65, which might be one of the underlying mechanisms of the inhibition of breast cancer cells proliferation and survival." (PMID 36142391, 2022). "TLR4 expression reportedly increased in various tumor cells including those involved in the development of non-small cell lung cancer, breast cancer and hepatocarcinoma." (PMID 34760363, 2021). "It was also suggested that TLR4/MyD88 levels could serves as a useful prognostic biomarker for breast cancer patients." (PMID 34671606, 2021). "Rebeca Santaolalla in a study on the breast cancer cells also showed that TLR-4 enhances migration of breast cancer cells, via PI3K/AKT/GSK3β, and promotes transcription of downstream-catenin target genes (MMP7, MMP9, and VEGFA), leading to breast cancer metastasis." (PMID 34904014, 2021). "The miR-370-3p level was dramatically increased in TLR4-activated breast cancer cells." (PMID 34475958, 2021). "TAK-242, a specific inhibitor of TLR4, was reported to considerably attenuate epithelial–mesenchymal transition (EMT) in ovarian and breast cancer cells by suppressing extracellular degradation through targeting TLR4 and regulating matrix metalloproteinase-2 (MMP-2) and MMP-9 expression." (PMID 33576897, 2021). "Moreover, a study revealed that activation of the MCF-7 and MDA-MB-231 breast cancer (BC) cell lines by LPS induces metastasis through TLR4, also suggesting a direct role of TLR activation on tumor cells." (PMID 34604233, 2021). "Signaling of TLR4 on mesenchymal stem cells in the TME, for instance, leads to suppression of NK cell cytotoxicity and MCP1 secretion, both associated with promotion of breast cancer cell migration." (PMID 34032639, 2021). "We used Target Scan Human as a bioinformatics tool for miRNA target prediction, focusing on a putative target, TLR4, which plays a significant role in breast cancer progression and metastasis and that has also been reported to be a direct target of miR-216a-5p in renal carcinoma." (PMID 32230799, 2020). "Previous evidence indicates that Toll-like receptor 4 contributes to the development of paclitaxel resistance in advanced breast cancer cells by increasing the expression of pro-inflammatory cytokines such as IL-6 and IL-8, as well as the anti-apoptotic protein XIAP." (PMID 33324567, 2020). "Our findings suggested that AT-I could inhibit NMU-induced mammary tumor progression in rats through inhibiting TLR4/NF-κB pathway." (PMID 33363472, 2020). "In summary, this study demonstrated that TLR4 and NF-κB were over expressed in breast cancer, and AT-I could suppress tumorigenesis of breast cancer via inhibiting TLR4-mediated NF-κB signaling pathway." (PMID 33363472, 2020). "Furthermore, in vivo studying demonstrated that AT-I suppressed tumorigenesis of breast cancer via inhibiting TLR4/NF-κB pathway." (PMID 33363472, 2020). "Then, we detected the effects of AT-I on the TLR4/NF-κB pathway in breast cancer cells." (PMID 33363472, 2020).
breast cancer (continued). "Furthermore, these differentially expressed levels of TLR4 and NF-κB were also detected in breast cancer cells and mammary epithelial cells." (PMID 33363472, 2020). "Our findings suggested that AT-I could inhibit NMU-induced mammary tumor progression in rats by inhibiting of TLR4/NF-κB pathway." (PMID 33363472, 2020). "AT-I could inhibit TLR4 mediated NF-κB signaling pathway and decrease NF-κB-regulated cytokines in breast cancer cells, thus inhibiting cell proliferation, migration and invasion, and inducing apoptosis of breast cancer cells." (PMID 33363472, 2020). "In another study, the effects of Chinese propolis (25, 50, and 100 μg/mL) and its major constituent (CAPE, 25 μg/mL) on inflammation-stimulated tumor and the Toll-like receptor 4 (TLR-4) signaling pathway, which plays a crucial role in human breast cancer cell line (MDA-MB-231), were evaluated." (PMID 33383693, 2020). "Several studies have been conducted to elucidate the links between TLR4 and breast cancer, and it has been shown that TLR4 is highly expressed in breast cancer cells and plays a crucial role in invasiveness, migration and angiogenic potential of cancer at primary or metastatic sites." (PMID 32230799, 2020). "AT-I is a novel TLR4-antagonizing agent, and it exerted anti-tumor effects on colorectal cancer, bladder cancer and melanoma, then we investigated whether it could suppress tumorigenesis in breast cancer via inhibiting TLR4/NF-κB pathway." (PMID 33363472, 2020). "Interestingly, very recently a report has emerged which establishes a role of resistin in inducing EMT and stemness of breast cancer cell, which it accomplishes by being a ligand for toll-like receptor-4 (TLR4), and by stimulating NF-κB-STAT3 signaling." (PMID 30131543, 2018). "The activation of TLR4 increases IL-8 and IL-6 production in breast cancer." (PMID 30213077, 2018). "In conclusion, our study demonstrates that TOPK is a key mediator in LPS/TLR4 signaling to trigger breast cancer invasion, and that LPS/TLR4 signaling enhances expression and activity of TOPK leading to NF-κB activation, thereby enhancing MMP9 expression and subsequent breast cancer cell invasion." (PMID 28212583, 2017). "Toll-like receptor 4 (TLR4) is well known for its host innate immunity, and recent evidence suggests that TLR4 is over-expressed in the majority of clinical breast cancer and involvement in breast cancer development and progression." (PMID 28950845, 2017). "Interestingly, both of expression of TOPK and TLR4 were markedly increased in high-grade breast cancer." (PMID 28212583, 2017). "Furthermore, we showed that silencing of TOPK abrogated LPS-induced MMP9 promoter-driven transcriptional activity as well as MMP9 protein level, resulting in suppression of breast cancer cell migration or invasion in LPS/TLR4 signaling." (PMID 28212583, 2017). "We provide evidence that TOPK might be a pivotal mediator in LPS/TLR4-mediated signal transduction pathways leading to breast cancer cell invasion." (PMID 28212583, 2017). "Furthermore, TLR4 has also been reported correlation with metastasis of breast cancer cells and has down favor on poor survival of breast cancer patients." (PMID 29029545, 2017). "We next asked expression pattern of TOPK and TLR4 in breast cancers." (PMID 28212583, 2017). "However, LPS/TLR4-mediated regulatory mechanisms for breast cancer progression still remain elusive." (PMID 28212583, 2017). "Immunohistochemical staining demonstrated that expression of TOPK or TLR4 was strongly correlated with breast cancer stage, and that expression pattern of TOPK or TLR4 was similar and significantly increased in high-grade breast cancer, invasive ductal carcinoma and lymph node metastasis." (PMID 28212583, 2017).